XRCC1 (X-ray repair cross complementing 1)
Diseases named in the same sentence as XRCC1 in open-access papers (continued):
Sharing a sentence is not in itself a finding about the gene and the disease.
esophageal cancer (9 papers, 2005 to 2021). A primary or metastatic malignant neoplasm involving the esophagus. "In treatment response analysis, we found that the XRCC1 rs25487 GA genotype was associated with reduced risk of minor treatment response in esophageal cancer." (PMID 34094945, 2021). "The distribution of the Arg399Gln polymorphism of XRCC1 was identified, and genotypes were studied in relation to both esophageal cancer and alcohol consumption." (PMID 26949387, 2016). "Regarding the XRCC1 Arg399Gln polymorphism our results show the evidence of associations between XRCC1 Gln399Gln genotype carriers and increased risk of cervical and esophageal cancer development, which is confirmed by other studies." (PMID 23675381, 2013). "Our study revealed that deletions of GSTT1 and GSTM1 genes or the distinct point mutations of XRCC1 gene are associated with cervical and esophageal cancers." (PMID 23675381, 2013). "A co-investigator (X.W.)found that the XRCC1 Arg399Gln SNP (BER) was associated with pCR in esophageal cancer patients treated with cisplatin-based RCT and surgery." (PMID 21586140, 2011). "Polymorphisms in XRCC1 have been associated with risk of many smoking-related cancers such as lung, bladder, and esophageal cancer." (PMID 16457697, 2005). "In treatment response analysis, high XRCC1 expression was associated with increased risk of minor treatment response in esophageal cancer (OR = 0.46, 95% CI: 0.24–0.88, P = 0.019) and in patients receiving radiotherapy only (OR = 0.36, 95% CI: 0.21–0.62, P = 0.000)." (PMID 34094945, 2021). "Recent data in esophageal cancer suggests the variant allele of a single-nucleotide polymorphism (SNP) in XRCC1 may be associated with resistance to radiochemotherapy." (PMID 21586140, 2011). "The XRCC1 Arg399Gln polymorphism does not appear to be associated with esophageal cancer in individuals of Korean or Han Chinese descent in Harbin, China." (PMID 26949387, 2016). "Studies have shown that esophageal cancer patients with negative XRCC1 protein expression have slightly higher responses to radiation than those with positive expression, suggesting that patients without XRCC1 protein expression may receive a superior benefit from radiotherapy to some extent." (PMID 34766149, 2021).
leukemia (9 papers, 2011 to 2026). A malignant (clonal) hematologic disorder, involving hematopoietic stem cells and characterized by the presence of primitive or atypical myeloid or lymphoid cells in the bone marrow and the blood. "The relationship between these XRCC1 polymorphisms and leukemia risk has been examined in some case­-control studies, but the results of these studies were contradictory and inconclusive." (PMID 24363792, 2013). "Based on three genetic models, the codominant model, dominant model and recessive model, odds ratios (ORs) as well as their 95% confidence intervals (CIs) were used to evaluate the association strength between XRCC1 genotypes and leukemia risk." (PMID 24363792, 2013). "We performed stratified analysis by leukemia type in order to clarify the role of XRCC1 polymorphisms in the development of individual types of leukemia." (PMID 24363792, 2013). "Three common X-ray repair cross-complementing groups 1 (XRCC1) polymorphisms, Arg399Gln, Arg194Trp, and Arg280His, have been reported to be implicated in the development of leukemia." (PMID 24363792, 2013). "Although the association between XRCC1 polymorphisms and risk of some types of leukemia was recognized by a number of studies, other reports did not take the XRCC1 genetic variants as risk or protective factors for leukemia." (PMID 24363792, 2013). "We conducted a meta-analysis that includes 19 studies for Arg399Gln (G>A) polymorphism, 12 studies for Arg194Trp (C>T), and 6 studies for Arg280His (G>A) to evaluate XRCC1 genotype-leukemia association." (PMID 24363792, 2013). "Meta-analysis and relevant subgroups analysis by tumor type, race and control sources were conducted to examine the association between XRCC1 Arg399Gln (G>A), Arg194Trp (C>T), and Arg280His (G>A) polymorphisms and leukemia risk in three genetic models." (PMID 24363792, 2013). "Therefore, a meta-analysis followed by stratified analysis of 19 published studies was performed to estimate the association between XRCC1 Arg399Gln, Arg194Trp, and Arg280His polymorphisms and leukemia risk." (PMID 24363792, 2013). "Statistical power (%) for XRCC1 polymorphisms and leukemia risk." (PMID 24363792, 2013). "Consequently, we performed a meta-analysis in order to accurately evaluate the association between XRCC1 Arg399Gln, Arg194Trp, and Arg280His polymorphisms and leukemia risk." (PMID 24363792, 2013). "Because the XRCC1 gene polymorphisms may alter DNA repair capacity, a number of studies have suggested that they might represent a risk factor in hematological malignancies such as leukemia." (PMID 24955348, 2014). "In the past decade, a number of studies have been performed to explore the relationship between three common XRCC1 single nucleotide polymorphisms (SNPs)—Arg399Gln (base G to A polymorphism), Arg194Trp (base C to T polymorphism), and Arg280His (base G to A polymorphism)—and leukemia risk." (PMID 24363792, 2013). "For instance, polymorphisms in the DNA repair gene XRCC1 have been associated with an elevated risk of both NPC and leukaemia in specific populations." (PMID 39529021, 2024). "Among them, XRCC1 Arg399Gln, Arg280His, and Arg194Trp, XRCC3 Thr241Met, and XPD Lys751Gln polymorphisms are the most studied in cancers, including leukemia." (PMID 24955348, 2014). "Analysis of leukemia-prone polymorphic alleles (XPA A23G, XPD Lys751Gln, XRCC1 Arg399Gln, XRCC3 Thr241Met, and RAD51 G135C) revealed an XPD and XRCC3-deficient heterozygous pre-SCT patient with normal alleles for XPA, XRCC1, and RAD51 DNA repair functions." (PMID 21951951, 2011). "However, it was noticed that XRCC1 polymorphisms play an important role in the development of ALL, and postnatal exposure to x-rays can modulate leukaemia risk in the presence of APEX1, MLH1, and XRCC4 gene variants." (PMID 26045716, 2015). "However, studies addressing the association between XRCC1 -77 T>C polymorphism and leukemia risk are absent, and cannot be analyzed by our meta-analysis." (PMID 24363792, 2013).
leukemia (continued). "Finally, African populations have not been well studied previously regarding XRCC1 polymorphisms and leukemia susceptibility." (PMID 24363792, 2013). "Taken together, results from this meta-analysis demonstrate that XRCC1 Arg399Gln, Arg194Trp and Arg280His polymorphisms might not be associated with overall leukemia risk." (PMID 24363792, 2013). "XRCC1 Arg194Trp, XRCC1 Arg399Gln, and XRCC3 Thr241Met polymorphisms were significantly associated with leukemia risk, while XRCC1 Arg280His was not." (PMID 42109639, 2026). "However, whether the XRCC1 polymorphisms in 3’UTR alter leukemia risk was not fully studied." (PMID 24363792, 2013).
liver cancer (9 papers, 2018 to 2024). An epithelial or non-epithelial malignant neoplasm that arises from the liver. "Our results showed that the XRCC1 Arg399Gln Gln/Gln genotype is a risk factor for liver cancer in the Chinese population." (PMID 30408066, 2018). "Surprisingly, we found that low ALDH2 expression levels associated with high XRCC1 expression levels are indicative for a poor overall survival, particularly in lung and liver cancer patients." (PMID 30088263, 2018). "Trial sequential analysis (TSA), false-positive report probabilities (FPRP), and combined genotype analysis revealed that XRCC1 Arg399Gln is mainly associated with susceptibility to liver cancer." (PMID 30408066, 2018). "We hypothesize that people exposed to risk factors for liver cancer are more likely to develop XRCC1 mutations, resulting in an altered DNA repair capacity and increased susceptibility to liver cancer." (PMID 30408066, 2018). "For genomic instability, a study has shown that ALDH2 suppression is associated with a higher DNA base excision repair protein (XRCC1, X-Ray Repair Cross Complementing 1) and worse survival in lung and liver cancers." (PMID 37476181, 2023). "The highest positive correlation of APE2 and XRCC1 occurred in liver cancer." (PMID 32111912, 2020). "Compared to normal liver tissue, the mRNA levels of XRCC1, MAPK3, and PCNA were significantly elevated in liver cancer tissue." (PMID 39346898, 2024). "Surprisingly we observed in this study, by using bioinformatics analyses, that most cancers, especially lung and liver cancers, gamble with lowering their expression of ALDH2 along with overexpressing XRCC1." (PMID 30088263, 2018). "In liver cancer patients, we observed a significant impact of ALDH2 mRNA expression on the overall survival rate, whereas the XRCC1 mRNA level itself had no predictive value." (PMID 30088263, 2018). "Therefore, we hypothesize that the XRCC1 Gln/Gln genotype can be used as a negative indicator in liver cancer and that XRCC1 can serve as a potential indicator for clinical diagnosis and prognosis, as well as a new potential target for clinical treatment in HCC cases." (PMID 30408066, 2018).
mucositis (9 papers, 2013 to 2024). Mucositis is inflammation and damage of the mucous membranes lining the mouth and other parts of the gastrointestinal (GI) tract. "- Risk of mucositis was increased in patients with XRCC1-399Gln allele genotypes both in the chemoradiotherapy (p = 0.035, HR = 1.72, CI = 1.03–2.86) and radiotherapy alone (p = 0.049, HR = 2.50, CI = 0.97–6.47) groups." (PMID 38473311, 2024). "For example, XRCC1 rs25487 (A>G) was associated with increased risk of acute dermatitis and mucositis as well as poor progression free survival in NPC patients after curative chemoradiotherapy." (PMID 28977945, 2017). "Another study showed that, in 114 patients with NPC, the XRCC1 rs25487 GA genotype was related with grade 3 dermatitis and grade 3 mucositis." (PMID 32684929, 2020). "Our literature review identified 27 candidate genes, of which ERCC1, XRCC1, and MTHFR were the most frequently studied for mucositis." (PMID 28678827, 2017).
xeroderma pigmentosum group D (9 papers, 2008 to 2023). Any xeroderma pigmentosum in which the cause of the disease is a mutation in the ERCC2 gene. "A number of genetic variants have been reported to be associated with radiotherapy response for cancer, including XRCC1, X-ray repair cross complementing 2 (XRCC2), xeroderma pigmentosum group D (XPD), and EGFR." (PMID 36624463, 2023). "Downregulation of GLI1 in cisplatin-treated ovarian cancer cells blocked the expression of c-JUN along with excision repair cross-complementing 1 (ERCC1), XRCC1 and xeroderma pigmentosum group D (XPD)." (PMID 26633513, 2015). "We studied the usefulness of the excision repair cross-complementing 1 (ERCC1), xeroderma pigmentosum group D (XPD), XRCC1 and GSTP1 polymorphisms as predictors of clinical outcome in these patients." (PMID 18797464, 2008). "For example, variants of genes involved in DNA repair, such as x-ray repair cross complementing 1 (XRCC1), XRCC3, human 8-oxoguanine DNA N-glycosylase 1 (hOGG1), and xeroderma pigmentosum group D (XPD), have been documented in schizophrenia pathophysiology." (PMID 30285728, 2018). "X-ray repair cross complementary 1 (XRCC1) is a major gene in the BER system, and xeroderma pigmentosum group A (XPA) and xeroderma pigmentosum group D (XPD) are two important genes in NER system." (PMID 20431719, 2010).
triple-negative breast carcinoma (8 papers, 2014 to 2025). An invasive breast carcinoma which is negative for expression of estrogen receptor (ER), progesterone receptor (PR), and human epidermal growth factor receptor 2 (HER2). "The obtained data suggest that the reported study may be the first observation of the polymorphisms in ERCC2, hOGG1, and XRCC1 genes, involved in the DNA repair pathway, to be associated with triple-negative breast carcinoma risk in the population of Polish women." (PMID 24402573, 2014). "Nonetheless, prior research has indicated that XRCC1 deficiency can lead to PARP1 hyperactivation, and notably, lack of XRCC1 expression has been reported in tumours, including triple-negative breast cancers." (PMID 41459749, 2025). "We previously identified STAT3 as a novel transcriptional regulator of X-ray cross-complementing group 1 (XRCC1), an essential scaffold protein in base excision repair in triple-negative breast cancers." (PMID 35457130, 2022). "Triptolide was shown to cause a decrease in the levels of PARP1, XRCC1, and RAD51 proteins in triple negative breast cancer cells, affecting single-strand break repair, base excision repair, and homologous recombination pathways." (PMID 33330091, 2020). "The aim of this study was to evaluate the role of the hOGG1-Ser326Cys (rs13181), XRCC1-Arg194Trp (rs1799782), and ERCC2-Lys751Gln (rs13181) gene polymorphisms with clinical parameters and the risk for development of triple-negative breast cancer." (PMID 24402573, 2014). "Also, berberine was able to increase the sensitivity of triple negative breast cancer cells to cisplatin, camptothecin, and methyl methanesulfonate by attenuating XRCC1-mediated repair of base excision and subsequently increasing double-stranded DNA breaks." (PMID 33330091, 2020). "In triple negative breast cancer, the constitutive activation of STAT3 upregulates XRCC1 gene and protein expression levels." (PMID 34067421, 2021).
lung adenocarcinoma (7 papers, 2009 to 2024). A carcinoma that arises from the lung and is characterized by the presence of malignant glandular epithelial cells. "We found that individuals carrying both ERCC1 118 and XRCC1 399 variant alleles were at a higher death risk of lung adenocarcinoma than those with only one of them (adjusted HRs were 2.44, 1.79 and 1.64, respectively)." (PMID 20003463, 2009). "In China, ERCC1 and XRCC1 were associated with the survival of non-smoker female lung adenocarcinoma patients." (PMID 23443124, 2012). "Increasing numbers of either ERCC1 118 or XRCC1 399 variant alleles were associated with shorter survival of non-smoking female lung adenocarcinoma patients (Log-rank P < 0.001)." (PMID 20003463, 2009). "Using the stepwise Cox regression analysis, we found that the polymorphisms in ERCC1 and XRCC1, tumor stage and chemotherapy or radiotherapy status independently predicted overall survival of non-smoking female patients with lung adenocarcinoma." (PMID 20003463, 2009). "This study aimed to investigate the relationship between polymorphisms in ERCC2, ERCC1 and XRCC1 genes and survival of non-smoking female patients with lung adenocarcinoma." (PMID 20003463, 2009). "This study showed that being advanced stage, without chemotherapy or radiotherapy, carrying variant genotypes at ERCC1 Asn118Asn or XRCC1 Arg399Gln were proved to be unfavorable prognostic factors for lung adenocarcinoma in Chinese non-smoking women." (PMID 20003463, 2009). "Genetic polymorphisms in ERCC1 and XRCC1 genes might be prognostic factors in non-smoking female patients with lung adenocarcinoma." (PMID 20003463, 2009). "In the Cox regression model, after adjusting for age, tumor stage, surgical operation and chemotherapy or radiotherapy, variant genotypes of ERCC1 118 or XRCC1 399 polymorphism were associated with higher risks of death for non-smoking female patients with lung adenocarcinoma." (PMID 20003463, 2009). "In the present study, we found that non-smoking female lung adenocarcinoma patients with AA genotype at XRCC1 Arg399Gln had a shorter survival time (9.23 months vs. 19.10 months) and higher risk of death (adjusted HR = 2.68, 95%CI = 1.79-4.02) than those with GG genotype." (PMID 20003463, 2009). "To test above possibility, we assess the relationship between survival of lung adenocarcinoma patients and SNPs in three DNA repair genes, including excision repair cross-complementing group 1 (ERCC1) and group 2 (ERCC2), and X-ray repair cross-complementing group 1 (XRCC1)." (PMID 20003463, 2009).
melanoma (7 papers, 2004 to 2023). A malignant, usually aggressive tumor composed of atypical, neoplastic melanocytes. "Loss of XRCC1 expression was correlated with the progression of melanoma from AJCC stage II to stage III and with worse overall and disease-specific 5-year and 10-year survival in 119 melanoma patients." (PMID 29312615, 2017). "We assessed the associations of polymorphisms and haplotypes in XRCC1 with skin cancer risk in a nested case–control study within the Nurses' Health Study (219 melanoma, 286 squamous cell carcinoma (SCC) and 300 basal cell carcinoma (BCC), and 873 controls)." (PMID 15381933, 2004). "In accordance with this hypothesis epidemiological studies of XRCC1 variants have associated Arg399Gln and Arg280His with an increased risk of developing melanoma and Arg399Gln and Arg194Trp with an increased risk of developing squamous cell carcinoma." (PMID 23247283, 2012). "Some of the genetic variants in the DNA repair gene XRCC1 have also been associated with melanoma." (PMID 22759494, 2012). "We assessed whether candidate polymorphisms and haplotypes in the XRCC1 gene are associated with skin cancer risk (melanoma, basal cell carcinoma (BCC), and squamous cell carcinoma (SCC)) in a nested case–control study within the Nurses' Health Study." (PMID 15381933, 2004). "Furthermore, XRCC1 expression has also been depicted as having an inhibitory effect on melanoma cell invasion and migration." (PMID 29312615, 2017). "We did not observe significant effect modification of the XRCC1 Arg399Gln on the relation of these risk factors with melanoma risk." (PMID 15381933, 2004). "Most notably, with MC1R, CAT and NOS1 genes in melanoma, HAL and IL23A genes in BCC and HAL and XRCC1 genes in SCC." (PMID 37537768, 2023). "We found some evidence of GxE interactions with sun exposure, notably, with MC1R, CAT and NOS1 genes in melanoma, HAL and IL23A in BCC and HAL and XRCC1 in SCC." (PMID 37537768, 2023).
squamous cell carcinoma (7 papers, 2004 to 2020). A carcinoma arising from squamous epithelial cells. "In this paper, we performed a systematic literature review to comprehensively evaluate the association between sequence variants in XRCC1 Arg399Gln and the risk of squamous cell carcinoma of the head and neck." (PMID 24205020, 2013). "In subgroup analyses, we observed an increased risk of XRCC1 399 Arg/Gln genotype for HNSCC in Caucasians (OR = 1.20, 95% CI: 1.00–1.44) and Gln/Gln genotype for larynx squamous cell carcinoma (OR = 1.63, 95% CI: 1.10–2.40)." (PMID 24205020, 2013). "However, XRCC1 Arg399Gln variants might be a potential risk factor for HNSCC among Caucasians and for larynx squamous cell carcinoma." (PMID 24205020, 2013).
xeroderma pigmentosum (7 papers, 2006 to 2025). Xeroderma pigmentosum (XP) is a rare genodermatosis characterized by extreme sensitivity to ultraviolet (UV)-induced changes in the skin and eyes, and multiple skin cancers. "Single nucleotide polymorphisms in xeroderma pigmentosum complementation groups C (Lys939Gln, A/C), D (XPD; Lys751Gln, A/C), and G (Asp1104His, G/C), and X-ray repair cross-complementing groups 1 (XRCC1; Arg399Gln, G/A) and 3 (Thr241Met, T/C) genes were genotyped." (PMID 16880786, 2006). "Moreover, polymorphism in several DNA repair genes, such as X-ray repair cross-complementing protein 1 (XRCC1), xeroderma pigmentosum group D 6 (XPD6) and 23 (XPD23), and cytochrome P450 1A1 (CYP1A1), was observed to be associated with high or medium DNA damage after exposure to air pollution." (PMID 40141439, 2025).